FASN (fatty acid synthase)
Diseases named in the same sentence as FASN in open-access papers (continued):
Sharing a sentence is not in itself a finding about the gene and the disease.
osteosarcoma (39 papers, 2013 to 2026). A usually aggressive malignant bone-forming mesenchymal neoplasm, predominantly affecting adolescents and young adults. "FASN is a putative diagnostic indicator for osteosarcoma and its inhibition induces cell growth arrest, apoptosis and reduced cell migration in U2-OS osteosarcoma cells." (PMID 33289496, 2021). "Additionally, USP2, recruited by VCP, enhances the stability of fatty acid synthase (FASN) by removing K48−linked ubiquitin chains, a process whose inhibition reverses pro-tumorigenic effects in osteosarcoma cells." (PMID 40370434, 2025). "These phenomena indicated that osteosarcoma cell proliferation and metastasis may be associated with the inhibitory effect of α-linolenic acid on FASN expression." (PMID 35566090, 2022). "It was speculated that the molecular mechanisms associated with the involvement of FASN in osteosarcoma proliferation and metastasis may be related to ER stress activation and the PI3K/Akt pathway." (PMID 35566090, 2022). "Besides, the upregulation of FASN was proved to be associated with the AR of osteosarcoma cells via p-ERK1/2/Bcl-xL." (PMID 34456997, 2021). "However, the role of FASN inhibition-induced ER stress, which is associated with osteosarcoma cell apoptosis, still remains unclear." (PMID 35566090, 2022). "FASN, a key enzyme in lipogenesis, is upregulated in pediatric tumors such as osteosarcoma, NB, and medulloblastoma." (PMID 40370434, 2025). "In osteosarcoma cells, the upregulation of FASN enhances cell anoikis resistance, and the knockdown of FASN significantly increases the rate of anoikis." (PMID 40014587, 2025). "For example, some studies indicate that FASN plays a crucial role in the progression and metastasis of osteosarcoma, making it a promising target for therapeutic interventions." (PMID 39445018, 2024). "It was found that a potential target for miR-320 is the E2F1 gene, regulating the cell cycle of osteosarcoma or fatty acid synthase (FASN) involved in OS metastasis." (PMID 36139691, 2022). "α-Linolenic acid, via downregulating FASN expression, induced human osteosarcoma MG63, 143B, and U2OS cell apoptosis in a dose-dependent manner." (PMID 35566090, 2022). "Then, we demonstrated that FASN was targeted by miR-195, which inhibited osteosarcoma cell proliferation, migration, and invasion." (PMID 35350838, 2022). "The findings of the present study suggested that α-linolenic acid suppresses osteosarcoma cell proliferation and metastasis by inhibiting FASN expression, which provides a basis as a potential target for osteosarcoma treatment." (PMID 35566090, 2022). "The protein expression of FASN of fresh osteosarcoma tissues was significantly higher than that of fresh normal bone tissue." (PMID 35350838, 2022). "The role of FASN in progression and metastasis development in osteosarcoma was demonstrated in previous studies." (PMID 35392503, 2022). "Our previous studies suggested that fatty acid synthase (FASN) was an oncogene and promoted osteosarcoma." (PMID 35350838, 2022). "A study had shown that α-linolenic acid, a polyunsaturated fatty acid, can inhibit the proliferation and metastasis of osteosarcoma cells by inhibiting the expression of fatty acid synthase." (PMID 36431859, 2022). "In this study, we identified FASN and miR-195 to be the potential therapeutic targets for osteosarcoma." (PMID 35350838, 2022). "PVT1 mainly acts as a competitive endogenous RNA (ceRNA) to negatively regulate miR-195 in osteosarcoma cells to enhance FASN expression, thereby promoting osteosarcoma cell migration and invasion." (PMID 34803512, 2021). "The lncRNA-PVT1 has been described to be upregulated in osteosarcoma promoting migration and invasion through the regulation of the miR-195/FASN axis." (PMID 33050166, 2020). "On the contrary, silencing the expression of lncPVT1 in osteosarcomas, augmented the effect of miR-195 on the inhibition of FASN expression." (PMID 33050166, 2020).
osteosarcoma (continued). "In conclusion, we showed that anoikis resistant and FASN as two interactional factors facilitated the progress of osteosarcoma." (PMID 30931932, 2019). "Our further work should focus on exploring the miRNAs regulating FASN and the effects and functions of these miRNAs in regulating osteosarcoma." (PMID 30931932, 2019). "Silencing lncRNA PVT1 expression can restore the inhibitory effect of miR-195 on FASN and thus inhibit the proliferation, migration, and invasion of osteosarcoma." (PMID 31757221, 2019). "miR-195 overexpression inhibited cell invasion and cell growth in osteosarcoma cells by targeting FASN." (PMID 29113367, 2017). "To date, several miRNAs have been reported to inhibit FASN expression, including miR-142-3p, miR-320, miR-424 and miR-195, but these studies were only carried out in osteosarcoma." (PMID 27713175, 2016). "Specifically, PVT1 negatively regulated miR-195 in osteosarcoma cells, and silencing PVT1 by siRNA suppressed BCL2, CCND1, and FASN protein expression via miR-195 in osteosarcoma cells." (PMID 27813492, 2016). "In osteosarcoma, FASN promotes anoikis resistance and metastasis to the lungs." (PMID 40370434, 2025). "Fatty Acid Synthase: Institutions under this cluster may wish to pursue therapeutic options through the role of fatty acid synthase in osteosarcoma." (PMID 39445018, 2024). "For example, osteosarcoma cells can increase lipid acid synthesis and storage by increasing lipid acid synthases such as fatty acid synthase (FASN) and lipoyl-CoA synthase (ACSL), which provide energy and raw materials required for tumor cell growth and biosynthesis." (PMID 37497349, 2023). "However, no previous studies have focused on the effect of α-linolenic acid on FASN activity in osteosarcoma cells." (PMID 35566090, 2022). "Our previous study showed silencing FASN could inhibit cell proliferation and migration of osteosarcoma." (PMID 35350838, 2022). "Thus, the present study aimed to determine whether α-linolenic acid could induce osteosarcoma cell apoptosis and investigate the underlying molecular mechanisms, and to reveal whether the mechanism of α-linolenic acid in anti-cancer activity may be related to FASN inhibition." (PMID 35566090, 2022). "The present study was designed to reveal the effects of α-linolenic acid on osteosarcoma and to reveal whether the mechanism of α-linolenic acid in anticancer activity may be related to FASN inhibition." (PMID 35566090, 2022). "FASN has also been proved to mediate AR during cell growth and metastasis in osteosarcoma." (PMID 34456997, 2021). "Furthermore, lncRNA PVT1 upregulation can promote the proliferation, migration, and invasion of osteosarcoma by regulating the miR-195/FA synthase (FASN) signaling pathway." (PMID 31757221, 2019). "A study has also highlighted the ability of PVT1 to simultaneously regulate multiple genes [BCL2 (B-cell lymphoma 2, apoptosis regulator), CCND1, FASN (fatty acid synthase)] through a single miRNA, miR-195, to inhibit apoptosis and cell cycle arrest while enhancing invasion in osteosarcoma." (PMID 29702599, 2018). "In addition, miR-320 was demonstrated to inhibit osteosarcoma cell proliferation by directly targeting fatty acid synthase." (PMID 28934982, 2017). "FASN is known as a therapeutic target in the treatment of osteosarcoma metastasis." (PMID 28060730, 2017). "PVT1 increased the expression levels of BCL2, CCND1 and FASN by inhibiting miR-195 in osteosarcoma." (PMID 27813492, 2016). "Lapatinib alters the malignant phenotype of osteosarcoma cells via downregulation of the activity of the HER2-PI3K/AKT-FASN axis in vitro suggesting that targeting signaling and the FASN axis could be detrimental for cancer cell survival." (PMID 27270654, 2016). "Moreover, silencing PVT1 by siRNA inhibited BCL2, CCND1, and FASN protein expression via miR-195 in osteosarcoma cells, and BCL2 inhibited the si-PVT1#1-induced apoptosis of U2OS cells." (PMID 27813492, 2016).
osteosarcoma (continued). "In the present study, it was hypothesized that FASN could be a potential target of osteosarcoma." (PMID 35566090, 2022). "Thus, FASN may be a potential target for the treatment of osteosarcoma, and α-linolenic acid could be an adjuvant drug for osteosarcoma therapy." (PMID 35566090, 2022). "Similarly, the expression of FASN in human osteoblasts is much lower than that in osteosarcoma cells According to some studies, inhibiting FASN in vivo or in vitro may suppress the proliferation of cancer cells." (PMID 35566090, 2022). "However, the molecular roles of FASN in osteosarcoma cells remain unclear and need to be further studied." (PMID 30931932, 2019). "Moreover, silence of FASN inhibited the lung metastasis of osteosarcoma." (PMID 30931932, 2019). "Moreover, miRNA-195 inhibited the migration and invasion of osteosarcoma cells via FASN." (PMID 27813492, 2016). "As for metabolic reprogramming, SPICE1 facilitates osteosarcoma progression by enhancing USP10-mediated deubiquitination and stabilization of FASN, thereby fueling lipid biosynthesis and tumor growth." (PMID 41522354, 2026). "In studies on the malignant progression of osteosarcoma, VCP recruits USP2 to act on FASN, removing the K48 polyubiquitin chains on FASN to block its degradation." (PMID 40936898, 2025). "Four ARGs-BRMS, COL4A2, FGF2, and OGT-were used to develop an RFS-predicting model, whereas seven ARGs-CD24, FASN, MMP2, EIF2AK3, ID2, PPARG, and PIK3R3-were used to develop an OS-predicting model in patients with osteosarcoma." (PMID 38217543, 2024). "Thus, the molecular mechanisms will be further studied and in vivo experiments will be performed to reveal the anti-metastatic properties of α-linolenic acid in tumor growth and metastasis, and determine whether FASN is a promising target and prognostic predictor for treating osteosarcoma." (PMID 35566090, 2022). "However, whether FASN could be a therapeutic target for osteosarcoma remains unknown." (PMID 35566090, 2022). "MG63 and SAOS2 cells expressed much greater levels of fatty acid synthase and stearoyl CoA desaturase 1 than MSCs, but these elevated enzyme levels significantly decreased in the V-BAP treated osteosarcoma cells prior to cell death." (PMID 33289496, 2021). "The inhibition of PVT1 had a cascading effect, in that it impeded miR-195 activity that then blocked fatty acid synthase (FASN), and, overall, the invasiveness of human osteosarcoma cell lines consequently decreased." (PMID 28353666, 2017). "Conversely, inhibition of FASN suppresses invasion and migration via downregulation of the activity of Her2/PI3K/Akt signaling in osteosarcoma cells." (PMID 29100311, 2017). "PVT1 consequently inhibits the apoptosis of osteosarcoma cells via miR-195/BCL2, induces cell-cycle arrest in osteosarcoma cells via miR-195/CCND1, and promotes the migration and invasion of osteosarcoma cells via miR-195/FASN." (PMID 27813492, 2016). "It has been reported that miR-195–5p could inhibit osteosarcoma cell migration and invasion through targeting FASN (fatty acid synthase)." (PMID 25775010, 2015). "However, whether miR-195 could target FASN in osteosarcoma and whether ectopic DNA methylation is the upstream regulatory mechanism of miR-195 in metastasis of osteosarcoma are not fully studied." (PMID 35350838, 2022). "However, whether miR-195 could target FASN in osteosarcoma was not fully studied." (PMID 35350838, 2022). "Immunoblotting of cell extracts demonstrated that FASN and SCD-1 levels were very low or non-detectable in human MSCs compared with the osteosarcoma cell lines." (PMID 33289496, 2021).
dyslipidemia (35 papers, 2010 to 2025). "In contrast, other studies have associated the increase in FASN expression with insulin resistance in metabolic syndrome rat model." (PMID 36985762, 2023). "HSD administration possibly protects from dyslipidemia through the downregulation of fatty acid synthase (FAS) and acetyl coenzyme A carboxylase alpha (ACCα), and upregulation of ATP-binding cassette transporters G8 (ABCG8) protein expressions in the liver." (PMID 40672362, 2025). "The effect of PG on liver function and dyslipidemia through its antioxidant potential and reduction of fatty acid synthase thought to be behind this positive effect." (PMID 31231500, 2019). "We found that a combination of free fatty acids, monosaccharides and insulin (‘metabolic syndrome’) together resulted in a >2-fold increase in FASN mRNA expression (p < 0.05)." (PMID 30250238, 2018). "Dyslipidemia induced by ritonavir associated with a shift in the liver expression of signature genes, Sterol Regulatory Element-Binding Protein (SREBP)-1 and fatty acid synthase." (PMID 20949026, 2010). "Western diet (e.g. high-fat diet, HFD) is one of the critical factors of HCE development, as it alters lipogenesis-linked enzyme expression (e.g. liver X receptor α/β, LXRa/β; acetyl-CoA carboxylase, ACC; and fatty acid synthase, FAS), consequently causing dyslipidemia." (PMID 41189665, 2025). "Consequently, HMC reduced hyperglycemia by improving the expression of insulin-resistance-related genes and improved dyslipidemia by regulating fatty acid synthase and oxidation-related genes in db/db mice." (PMID 35565920, 2022). "Dyslipidemia might be explained by an increase in hepatic mRNA expression of Cyp7a1 and fatty acid synthase, while lipid efflux of PHD3dko macrophages was comparable to controls." (PMID 34055796, 2021). "FASN is considered a front-line drug target for the treatment of metabolic syndromes, cancer, and HCV, and data from this report suggest that FASN could be targeted in anti-HIV therapy." (PMID 28962653, 2017). "Additionally, considering that FASN and ACLY contribute to hepatic lipogenesis, our results suggest a potential mechanism for the dyslipidemia in adult male mice that is associated with TFA diets." (PMID 29237473, 2017). "We do not exclude the possibility that mRNA FASN levels may be also associated with metabolic parameters in pregnant women with comorbidities, such as gestational diabetes, hypertension or dyslipidemia." (PMID 27090298, 2016). "A study showed that the expression level of fatty acid synthase (FASN) in the liver was positively correlated with lipid accumulation in obese model mice, suggesting its key role in high-fat diet (HFD)-induced metabolic syndrome." (PMID 41019065, 2025). "However, FK506 could induce dyslipidemia by upregulating FASN during liver transplantation." (PMID 40046057, 2025). "Consistently, a previous study demonstrated that ursolic acid decreased SREBP-1c, FASN, and ACC1 expression levels via activating PPARα in the liver, alleviating liver lipid accumulation and dyslipidemia in obese rats." (PMID 39942052, 2025). "C/EBPb, FASN, SCD1, Bax and Caspase-3 were highly expressed in metabolic syndrome, and their expression levels were down-regulated after exercise." (PMID 37053002, 2023). "The network pharmacology studies showed that FASN, SCD1 (SCD) and SREBP1 (SREBF1) are targets for the treatment of postmenopausal dyslipidemia by TKRDF." (PMID 35872979, 2022). "We previously showed that the specific PPARα agonist fenofibrate, an FDA-approved drug used to treat dyslipidemia with minimal activity toward PPARγ, upregulated PPARα target genes in the DRG and rescued the impaired axon growth in mice lacking fatty acid synthase in SGC." (PMID 34586065, 2021).
diabetes (33 papers, 2010 to 2025). "We have now shown that hepatic FASN deficiency ameliorated NAFLD and diabetes in Mc4r-KO mice by suppressing DNL, FAO, and gluconeogenesis and improving hepatic insulin signaling without inducing hypertriglyceridemia." (PMID 37681411, 2023). "Positive expression of FASN was associated with lymph node metastasis, TNM stage, histological grading, diabetes, and body mass index." (PMID 34123778, 2021). "Gene expression of other insulin-responsive metabolic enzymes, including transcription factors Forkhead Box O1 and O6 (FoxO1, 6) and the fatty acid transporter, CD36, and fatty acid synthase were both modulated by diabetes but were unaffected by SRT3025." (PMID 30228292, 2018). "It is known that the fatty acid synthase enzymes can become defective in diabetes." (PMID 39852368, 2025). "Hepatic FASN deficiency in Mc4r-KO mice ameliorates NAFLD and diabetes." (PMID 37681411, 2023). "Several studies had shown that miRNA could inhibit inflammation by targeting FASN to improve the progression of diabetes complications." (PMID 36741233, 2023). "Collectively, these findings suggested that hepatic FASN deficiency in Mc4r-KO mice suppresses FAO and gluconeogenesis in association with augmentation of insulin signaling, which together may ameliorate diabetes." (PMID 37681411, 2023). "Later, it was discovered that both the m6A level and METTL3 expression were increased in the livers of patients with type 2 diabetes mellitus (T2DM), and their expression was positively associated with IR by promoting the expression of fatty acid synthase (Fasn)." (PMID 35692393, 2022). "In addition, we also found that the positive expression of FASN was significantly correlated with diabetes and body mass index." (PMID 34123778, 2021). "FASN-mediated de novo fatty acid synthesis affects the retention of plasma membrane cholesterol and Rho GTPase trafficking, which is important for adhesion, migration and activation of macrophages in diabetes." (PMID 34642298, 2021). "This implicates FASN as an important regulator of diet-induced diabetes." (PMID 29463677, 2018). "However it could become significant in diabetes, perhaps as a compensatory mechanism, since we showed that de novo lipogenesis and fatty acid synthase are induced in islet from ZDF rats." (PMID 24130841, 2013). "GCG, IRS1, VEGFA, STAT3, CCL2, CASP3, and APOE as diabetes mellitus-related proteins and SREBF1, LPL, PPARA, APOB, GPT, MAPK8, and FASN as NAFLD-specific proteins were identified as possible discriminating factors between the two studied diseases." (PMID 35154608, 2021). "SREBP is involved in the regulation of various lipogenic genes such as ACACA, FASN, ACSL1 and MCAT which are found to be overexpressed in diabetes." (PMID 31569751, 2019). "Hepatic FASN deficiency thus ameliorated NAFLD and diabetes in melanocortin 4 receptor–deficient (Mc4r-KO) mice but not in mice fed a high-fat diet (HFD)." (PMID 37681411, 2023). "Furthermore, fatty acid synthase (FAS), the key de novo lipogenesis enzyme, has increased activity in the setting of diabetes and was proven to contribute to atheroprogression in carotid arteries of patients by changing lipid species levels." (PMID 36624524, 2023). "Fatty acid synthase (FASN) activity may partly account for the link between ErbB2 and diabetes because the overexpression of ErbB2 through a phosphatidylinositol 3'-kinase-dependent pathway promotes the expression of FASN29." (PMID 35322023, 2022).